BRCA1 (BRCA1 DNA repair associated)
Diseases named in the same sentence as BRCA1 in open-access papers (continued):
Sharing a sentence is not in itself a finding about the gene and the disease.
tumor (continued). "Treatment of p18−/−; Brca1MGKO tumor cells including both type 1 and type 2 cells with AZD5363 significantly reduced the E2-enhanced number of cells and incorporation of BrdU, indicating that AZD5363 inhibits estrogen-enhanced proliferation of Brca1-deficient tumor cells." (PMID 29996906, 2018). "Furthermore, we propose a model of how transcriptional regulation could contribute to tissue-dependent tumor-suppressing function of BRCA1." (PMID 30558184, 2018). "Importantly, our in vivo results showed that tumor-bearing mice harboring the same Brca1 mutation (Brca1-Δ11) exhibited non-uniform responses to vinblastine." (PMID 30327455, 2018). "However, in contrast to 53BP1 loss, which can restore HR repair to BRCA1-deficient tumors, USP48 loss is not an expected mechanism of tumor resistance in BRCA1 patients as hyper-resection following USP48 loss requires BRCA1 function." (PMID 29335415, 2018). "Transplantation of ER-positive p18−/− tumor cells into NSG mice did not produce tumors, whereas, with exogenous E2 supplement, p18−/− tumor cells generated ER-positive tumors in NSG mice, suggesting that host estrogen is not sufficient to induce p18 deficient, Brca1-proficient tumor initiation." (PMID 29996906, 2018). "First, the expression of BRCA1/2 genes in the tumor may be repressed by hypermethylation of gene promoter, or BRCA1/2 genes may display somatic mutations, even though the impact of these alterations on PARP inhibitors and/or platinum sensitivity remains elusive." (PMID 30544963, 2018). "Hence, olaparib alone had no obvious effect in killing tumor cells without BRCA1/2 mutations, unless it was used at high concentrations." (PMID 29479816, 2018). "We treated p18−/−;Brca1MGKO tumor cells with E2 in multiple time periods and observed by western blot that E2 stimulated expression of Vim and EMT-TFs including p-Fra1 and/or Snail/Slug in both type of cells, indicating E2 promotes EMT in Brca1-deficient tumor cells in vitro." (PMID 29996906, 2018). "Our results indicate that BRCA1 deficiency caused by somatic mutation or promoter methylation of BRCA1 in sporadic ER-negative breast cancers sensitizes tumor cells to endogenous estrogen activating EMT, promoting CSCs and, therefore, inducing tumor progression." (PMID 29996906, 2018). "Additionally, patients with sporadic TNBC without BRCA mutation show BRCA1 mutation-like tumor conditions (“BRCAness”) in which BRCA is inactivated by other mechanisms such as promoter methylation or gene expression inhibition." (PMID 29448954, 2018). "The role of BRCA1 in histone ubiquitination could contribute to its tumor suppressor function." (PMID 30558184, 2018). "Inevitably, there have been substantial changes in the management of BRCA1 and BRCA2 mutation carriers since the recruitment period of this study, including the exploration in trials of systemic therapies that exploit BRCA-null tumours, including platinum-based drugs and PARP inhibitors." (PMID 29337092, 2018). "We show that BRCA1 binds to putative cis-elements in promoter regions of the miRNAs with the potential to regulate their expression, and that four miRNAs (miR-29b-1-5p, miR-664, miR-16-2 and miR-744) significantly stratified the overall survival of basal-like tumours." (PMID 30323900, 2018). "Interestingly, we found that BRCA1 mutated tumours presented a potent immunogenic phenotype, independent of TMB, meeting the criteria of both our dominant factors and the determinants of immunogenicity established before." (PMID 29855141, 2018). "In addition, it has also been suggested that inhibitors of BRCA1 may sensitize tumor cells to the effect of targeted therapies such as PARP1 inhibitors." (PMID 29606576, 2018).
tumor (continued). "Taken with evidence from clinical trials, which demonstrate no benefit from SERMs in reducing the incidence of ER-negative tumours, this suggests that SERMs are unlikely to be effective chemopreventive agents in BRCA1 mutation carriers (who are more likely to develop ER-negative tumours)." (PMID 30580266, 2018). "Estrogen activated EMT independent of ER in Brca1-deficient, but not Brca1-proficient, tumor cells." (PMID 29996906, 2018). "From a biological rationale perspective, it is envisaged that PARP inhibitors are active irrespective of whether a BRCA1/2 variant is of germline or somatic origin as both result in the loss of function of both copies of BRCA1 or BRCA2 in the tumor." (PMID 29215764, 2018). "The tumor assay used here identified 10% (20/209) of patients with somatically mutated tumors that would not be detected by germline testing and enables BRCA1/2 testing of clinical FFPE specimens with a sensitivity, cost, and sample input that cannot be achieved by Sanger sequencing techniques." (PMID 28525389, 2017). "In addition, breast cancer 1 (BRCA1) is a tumor suppressor located close to Beclin-1 on the genome." (PMID 28753959, 2017). "One reason for this is the lack of isogenic controls, as non-BRCA1/2 mutant tumour samples have a range of different somatic mutations, and may even have affected BRCA1/2 expression." (PMID 27452521, 2017). "In addition, we presented separate analyses for ORR of primary tumor and neck nodes based on BRCA1 and ERCC1 expression in primary NPC in order to assess whether or not the different treatments affect the primary tumor and the metastatic sites." (PMID 28404895, 2017). "However, it can be speculated that BRCA1 promoter hypermethylation is heterogeneous within the tumor." (PMID 29137324, 2017). "Interestingly, the majority of cases with low BRCA1 N/C ratio (~60%) was associated with high ki67 LI (p b = 0.007) and basal nature of the tumor (p b = 0.02) (not tabulated)." (PMID 28863181, 2017). "Therefore, for TNBC patients, who share a considerable overlap in BRCA1 mutation, in the context of BCS, RT to the breast and surrounding tissue could eradicate recessive BRCA1-deficient tumor lesions and thereby decrease LRR." (PMID 27999201, 2017). "Additionally, the level of methylation of normal and tumor samples was analyzed according to the mutational status of BRCA1 (mutated vs. non-mutated)." (PMID 27926510, 2017). "Thus, it appears that tumor expression of CTSO may play a role in the regulation of BRCA1 transcription in addition to having an effect on BRCA1 protein degradation." (PMID 28968398, 2017). "We first tested the ability of isogenic BRCA1+/+ and BRCA1mut/+ cells to survive and proliferate as floating colonies in serum-free, anchorage-independent conditions, a widely employed in vitro assay of the self-renewal and tumor-initiating capacity of CSC-like cells." (PMID 28388533, 2017). "Moreover, in our cohort, four phenocopies also developed other tumours, which are not usually associated with the BRCA1/2 phenotype." (PMID 28199346, 2017). "The prevalence of BRCA1-IRIS overexpression amongst the Egyptian TNBC patients compared to the non-TNBC patients (65% vs. 28%) strongly suggests a tumor-promoting role, while its association with node and distant metastasis suggests metastatic driver role as well in TNBC patients." (PMID 28499366, 2017).
tumor (continued). "Furthermore, it has been shown that BRCA1 mutant tumours tend to overexpress immune response genes." (PMID 26943587, 2016). "The term ‘BRCA-ness’ similarly refers to tumours in which no germline BRCA1 mutation has been identified but which share histopathological features frequently found in BRCA1 mutated tumours, including a high mitotic index, pushing borders, syncytial and circumscribed growth patterns." (PMID 27463681, 2016). "However, it has been suggested that BRCA1 may exert tumour suppressive effects by repression of c-Myc activated genes and while the tricomplex of BRCA1/Nmi/c-Myc represses hTERT transcription, c-Myc alone transcriptionally activates hTERT." (PMID 27487152, 2016). "However, although all tumors in the present study were BRCA1-associated, and in theory should respond to cisplatin with the apoptosis of tumor cells, 40% of them did not exhibit pCR after neoadjuvant chemotherapy with cisplatin." (PMID 27626685, 2016). "Taking into account the implications for both the individuals and their family members, we recommend that patients with these neoplasias may be offered BRCA1/BRCA2 genetic testing and we here show that it is feasible to reliably perform this analysis in FFPE tissue." (PMID 27532258, 2016). "However, the co-existence of BRCA1 constitutive mutation and HER2 (even moderate) amplification have never been checked for the second genomic event required for the development of a hereditary tumor: BRCA1 wild type allele inactivation." (PMID 26426992, 2015). "This new mechanism may explain not only the development of tumors that lack mutations or alterations in tumor suppressors involved in DNA damage repair and response but also the overexpression of RAD51 found in a wide variety of human tumors, including BRCA1-deficient ones." (PMID 26282282, 2015). "It seems likely that the sensitivity of BRCA defective tumour cells to PARP inhibitors is caused by their characteristic defect in repair of DNA double strand breaks (DSBs) by homologous recombination (HR), a process controlled by BRCA1, BRCA2 and the DNA recombinase RAD51." (PMID 25883215, 2015). "In this study, we compared MD in BRCA1/2 mutation carriers and non-carriers from BRCA1/2 mutation-positive families and investigated the association between MD and BC among BRCA1/2 mutation carriers per type of mutation and tumor subtype." (PMID 26163143, 2015). "In this study we also found that BRCA1-haploinsufficient epithelial cells, but not fibroblasts, undergo a novel form of premature senescence associated with haploinsufficiency rather than loss of a tumour suppressor." (PMID 26106036, 2015). "We then determined whether a correlation between PIG3 and BRCA1 exists by using tumor microarrays." (PMID 25797244, 2015). "Interestingly, preclinical and clinical trials have been successful not only in tumours with deficiencies in the double-stranded DNA repair, such as mutations in BRCA1 and BRCA2, but also in tumours that have no defects in the HRR." (PMID 26339143, 2015). "BRCA1 mRNA and protein in situ expression, as well as the amount of BRCA1 ligated to BARD1 in the tumor, lacked any associations with patient outcomes, likely due to high intratumoral heterogeneity, and thus could not be used for clinical purposes." (PMID 26490435, 2015). "As patients with tumours that harbour a somatic BRCA mutation may also benefit from treatment with PARP inhibitors, it is important to be able to test for BRCA1 and BRCA2 variants in tumour samples available after routine histopathology assessment and diagnosis." (PMID 25859162, 2015).
tumor (continued). "Also in the studies included in this review, there were many differences reported in tumour characteristics between BRCA1 and also BRCA2 mutation carriers compared to ‘non-carriers’ (part A)." (PMID 25816289, 2015). "Since Nrf2-deficient mice exhibited a relative increase in the formation of tumor foci in the urethane-induced lung carcinogenesis model, loss and/or reduction of NRF2 activity by BRCA1 deficiency may contribute to the carcinogenesis of BRCA1-associated tumors." (PMID 24704793, 2014). "However, the concurrent silencing of Aur A/B and BRCA1/2 diminished the effects of these molecules on the regulation of cell cycle, cytokinesis, and tetraploidy, leading to the burdened tumor sizes similar to those induced by scrambled shRNA-treated control cells." (PMID 24775809, 2014). "However, much less is known about familial tumours (the remaining 5-7%), although studies have noted that BRCA1 tumours are predominantly basal-like while BRCA2 tumours are more hetergeneous and may be HER2-enriched or luminal-like." (PMID 25521701, 2014). "Moreover, somatic mutations in at least one of the BRCA genes are present in a significant proportion of sporadic HGSOC, rendering BRCA1 and BRCA2 as two of the most frequently mutated tumor suppressor genes that guard against the transformation of serous epithelium to HGSOC." (PMID 24624361, 2014). "BRCA1 is a multifunctional protein involved in many fundamental cellular processes including cell cycle regulation, DNA repair, transcription, chromatin modifications and ubiquitylation, all contributing to its role in maintenance of genomic stability and tumor suppression." (PMID 25460500, 2014). "In patients with BRCA1/2 deficient cancers, one such approach has been to develop molecular targeted therapy using PARP inhibitors that selectively exploit biological pathways within tumour cells, which differ from those in normal cells and wider concepts of genetic synthetic lethality." (PMID 25526776, 2014). "This could represent a new mechanism by which BRCA1 may exert tumor suppressor function." (PMID 25010005, 2014). "Since caveolin-1 was found to translocate to the plasma membrane in the presence of BRCA1/BRCA1a proteins, we can speculate that this may provide an important mechanism for regulating the tumor suppression function in sporadic ovarian cancers where somatic mutations in BRCA1 are rarely found." (PMID 25594072, 2014). "Overall, these findings are in agreement with our findings regarding the BRCA1-3’UTR-variant, that reduced BRCA1 expression in the absence of germ-line protein coding sequence variants may be associated with aggressive tumor biology." (PMID 24915755, 2014). "Alternatively, genome-wide tumor-methylation profiles may prove of value to distinguish between individual with and without a germline BRCA1 mutation." (PMID 25857409, 2014). "It is important to investigate the functional linkage between PTEN and BRCA1 in those ovarian samples, and elucidation of interaction-specific functions may provide insight into regulatory aspects of these tumor suppressors as well as opportunities for therapeutic intervention." (PMID 25426449, 2014). "There was a general decrease in proliferation in tumors treated with cisplatin or the combination of cisplatin and olaparib compared to vehicle in both Brca1-deficient tumor models, but not in the Brca1-wild type model, even though Brca1-wild type model was treated for a longer time (3 weeks)." (PMID 24748377, 2014). "However, a comprehensive analysis of PARP-1 activity, BRCA1 promoter methylation and 53BP1 expression in tumours without known BRCA1 mutation has not yet been carried out." (PMID 24191908, 2013).
tumor (continued). "Even though it was found to be highly influenced by molecular tumor subtypes (which are highly correlated with hormone receptor expression), the gene-expression-based classification seemed to be able to capture additional hormone-receptor-independent–BRCA1-related biological information." (PMID 23704984, 2013). "Moreover, uterus hyperplasia and increased carcinogen-induced tumorigenesis in mice carrying a targeted mutation of the Chk2 phosphorylation site in BRCA1 has been reported, suggesting that Chk2 phosphorylation is involved in the BRCA1 function in repressing tumor formation." (PMID 23388117, 2013). "This correlation between ERCC1 or BRCA1 expression and CRC metastasis has been suggested recently, but no statistical association could be established between reduced expression of ERCC1 or BRCA1 and tumor stage and lymph node involvement." (PMID 23496813, 2013). "This is no exception for BRCA1 mutation associated tumor development." (PMID 23388117, 2013). "Initially it was demonstrated that ATM a well known tumor suppressor which belongs to the family of proteins related to phosphoinositide kinases, physically interacts with BRCA1 in irradiated cells, and that it specifically phosphorylates BRCA1 at serine residues 1423, 1524 and 1457." (PMID 24832651, 2013). "Although our BRCA1 knockdown and reconstitution studies in cell lines are consistent, reliance on in vitro models may not accurately reflect the in vivo scenario where cell–stromal interactions and immunoediting will significantly impact on tumour behaviour." (PMID 23863842, 2013). "However, the sensitivity and reliability of such biomarkers may be complicated by mutations in the BRCA1 or BRCA2 genes, diverse genetic risk factors, unidentified initiation and progression elements, molecular tumor heterogeneity and disease staging." (PMID 22481932, 2012). "Thus, suppression of the oncogenic activities of c-Myc may account for some of the tumor suppressor activity of BRCA1." (PMID 22737296, 2012). "Within such a context low FMR1 alleles not only may overcome embryo lethality (i.e., growth arrest) in human embryos but may also have a similar function in the induction of BRCA1/2-associated malignancies by overcoming the natural growth arrest functions of BRCA1/2 by inducing tumor growth." (PMID 22984553, 2012). "It is of some interest that it is not yet known whether the absence of Brca1 itself is the driver of tumor growth (by an unknown mechanism), or whether mutations induced by repair deficiencies are the source of the tumors." (PMID 22347416, 2012). "Lakhani and colleagues argued previously that the use of CK in combination with ER status may provide a more specific test for BRCA1 carrier status than ER alone, because ER-negative tumours are more frequently observed amongst control tumours than are basal CKs." (PMID 20482762, 2010). "This absence of distinct patterns of mRNA or miRNA expression in groups with different BRCA1 status may reflect the rapid divergence in tumors once they acquire chromosomal instability, so that every individual tumor is sufficiently unique that clustering analysis identifies no patterns." (PMID 20843305, 2010). "Similarly, the presence of an ER-positive tumour in the family may result in combined BRCA1 and BRCA2 carrier probabilities <20%." (PMID 20482762, 2010).